TYMS (thymidylate synthetase)
Diseases named in the same sentence as TYMS in open-access papers (continued):
Sharing a sentence is not in itself a finding about the gene and the disease.
breast cancer (48 papers, 1995 to 2026). A primary or metastatic malignant neoplasm involving the breast. "The impact of single nucleotide polymorphisms (SNPs) in the TYMS enzyme in the risk of breast cancer has been investigated among most ethnic background populations in the world, but not among women of Kurdish Iraqi populations." (PMID 34048185, 2021). "This study is the first attempt to examine polymorphisms in the 5’-UTR and 3’-UTR region of the TYMS gene and its association with breast cancer for patients in the Kurdistan Region of Iraq." (PMID 34048185, 2021). "For the first time, this study intends to obtain the Kurdish TYMS gene polymorphism and to study the relative contribution of its variants to breast cancer risk in the Iraqi Kurdish population." (PMID 34048185, 2021). "Previously reported race and survival-associated genes including MUC1, GSTT2, PSPHL, SQLE, and TYMS were associated with race in this population-based study of women diagnosed with breast cancer." (PMID 29228969, 2017). "Genetic variants of TYMS (thymidylate synthetase) involved in folate-mediated one-carbon metabolism in DNA synthesis have been recently reported in breast cancers." (PMID 26975659, 2016). "In this hospital-based case-control study, we investigated the associations of one promoter SNP TSER and a TS 3'-UTR del6 polymorphism in the 3'-UTR of the TYMS gene with risk of breast cancer in a Chinese population." (PMID 16723031, 2006). "In addition, TYMS is associated with tumor metastasis and aggressive phenotypes of several tumors, such as glioma, breast cancer, prostate cancer, and soft tissue sarcoma." (PMID 35093082, 2022). "The study was conducted to evaluate whether 2R/3R and 6bp insertion/deletion polymorphisms of the TYMS gene are associated with breast cancer risk in the Kurdish Iraqi population." (PMID 34048185, 2021). "Specifically, we sought to estimate differences in the expression of two suspected good prognosis genes (ACOX2 and MUC1) and six suspected poor prognosis genes (FAM177A1, GSTT2, PSPH, PSPHL, SQLE, and TYMS) by race, and to examine their associations with risk of breast cancer recurrence." (PMID 29228969, 2017). "Because age, menopausal status, age at menarche, age at first live birth and family history of cancer were the well accepted risk factors for breast cancer, we performed stratification analyses by these variables to assess risk modification by the TYMS genotypes." (PMID 16723031, 2006). "Therefore, genetic alterations in TYMS enzyme efficiency and/or expression level may contribute to individual susceptibility to breast cancer." (PMID 16723031, 2006). "Because TYMS plays an important role in folate metabolism, which is essential for DNA methylation, synthesis, and repair, our findings provide some evidence for the underline molecular mechanism of the association between folate metabolism and breast cancer susceptibility." (PMID 16723031, 2006). "In conclusion, our study reveals that everolimus sensitizes breast cancer to fluoropyrimidines by destabilizing TYMS through modulation of its O-GlcNAcylation." (PMID 41935067, 2026). "The mRNA from cyclin D1 (CCND1) and thymidylate synthase (TYMS) served as reliable predictive biomarkers in breast cancer." (PMID 37091783, 2023). "TYMS expression was elevated in breast cancer compared with normal tissues, and was greater in TNBC than non-TNBC, and higher TYMS was associated with poor prognosis." (PMID 37046596, 2023). "Our results agree with the previously demonstrated putative SP1 binding motif on tyms promoter in MCF-7 breast cancer cells, wherein the regions −229/−140 and −145/−124 were investigated and found to be responsible for the high basal activity of TYMS." (PMID 37894370, 2023). "Several studies have reported an association between TYMS 5’-UTR and 3’-UTR polymorphisms and breast cancer risk, but contradictory results were obtained in different studies." (PMID 34048185, 2021).
breast cancer (continued). "The results of this study showed that only the DD genotype for 6bp deletion in 3’-UTR of the TYMS gene was significantly more frequent in breast cancer patients than in the healthy controls." (PMID 34048185, 2021). "TYMS is also a target gene of three Breast cancer drugs (Fluorouracil, Gemcitabine and Capecitabine) and physically interacts with two genes from the Triple Negative pattern -NUF2 and NDC80." (PMID 26892392, 2016). "As TOP2A, TYMS is also a gene from the Triple Negative pattern which is a target gene of three Breast cancer drugs (Fluorouracil, Gemcitabine and Capecitabine)." (PMID 26892392, 2016). "TOP2A and TYMS were found significant up-regulated genes in Triple Negative breast cancer cells, as compared to normal cells." (PMID 26892392, 2016). "We selected five genes (CAV1, DHFR, TYMS, VIM, ZEB1) known to be associated with drug sensitivity and the epithelial-mesenchymal transition of breast cancer." (PMID 21501481, 2011). "TYMS is found to be up-regulated in breast cancer, lung cancer, liver cancer and prostate cancer." (PMID 34141464, 2021). "Similarly, patients with breast cancer showing high TYMS expression have a poor prognosis." (PMID 38719775, 2024). "TYMS is overexpressed frequently in different kinds of cancers, such as NSCLC, pancreatic, colorectal, and breast cancers, and it has resulted in a poor cancer prognosis and chemotherapy resistance via dysregulating pyrimidine metabolism." (PMID 33344071, 2020). "TYMS physically interacts with two genes from the HER2 pattern -CENPO and CENPA and is a target gene of three Breast cancer drugs (Fluorouracil, Capecitabine and Gemcitabine)." (PMID 26892392, 2016). "Importantly, this combination strategy was effective in refractory breast cancer patients, and decreased levels of TYMS and OGT were observed in breast cancer patient specimens collected before and after everolimus-containing treatment." (PMID 41935067, 2026). "Serum samples from 154 dogs with mammary tumors (31 benign, 123 malignant) and 39 healthy controls were analyzed using a custom multiplex immunoassay detecting autoantibodies against AGR2, HAPLN1, IGFBP5, and TYMS, normalized to anti-BSA levels." (PMID 41562247, 2026). "Thus, many studies have shown that the expression and/or co-expression of several genes, such as ERCC1, RRM1, TOP1, TOP2α, TUBB3, TYMS, and GSTP1, in tumor tissues is closely related to chemoresistance and prognosis in breast cancer patients (BC)." (PMID 35204496, 2022). "Unfortunately, there have been few studies about the roles of TYMS and HIST1H2BF in breast cancer." (PMID 31641220, 2019).
gastric cancer (35 papers, 2000 to 2026). A primary or metastatic malignant neoplasm involving the stomach. "For instance, MKI67 is a potential indicator to predict the prognosis of patients with stomach cancer and identify high-risk cases, and TYMS may be potential biomarkers for prognosis and chemotherapy guidance for stomach cancer." (PMID 36226184, 2022). "TYMS overexpression is associated with poor disease-specific survival and local recurrence-free survival of various solid tumors such as lung cancer, gastric cancer and prostate cancer." (PMID 35003215, 2021). "The UGT1A1 polymorphism may be useful to screen the risk population of gastric cancer, while TYMS, TUBB3 and STMN1 may be potential biomarkers for prognosis and chemotherapy guidance." (PMID 28056823, 2017). "Our findings suggest UGT1A1 polymorphisms may be useful to screen the risk population of gastric cancer and schedule the appropriate pretreatment to improve the overall survival, while TYMS, TUBB3 and STMN1 may be potential biomarkers for prognosis and chemotherapy guidance." (PMID 28056823, 2017). "The analysis of the PRISM data also identified the interaction between the driver gene KMT2C and the drug Capecitabine, an oral prodrug of 5-fluorouracil that targets TYMS and is commonly used in the treatment of advanced gastric cancer 48,49." (PMID 37737478, 2023). "IQGAP3 promotes tumor migration and invasion in the ovarian and gastric cancers Inhibiting TYMS promotes the proliferation, migration, and invasion of the cervix." (PMID 36750200, 2023). "5-FU, the most widespread antimetabolite in cancer chemotherapy, can attenuate DNA synthesis via the inhibition of thymidylate synthetase in gastric cancer cells." (PMID 30038550, 2018). "This was consistent with the research finding that elevated expression of CHAF1A could promote thymidylate synthetase activity, leading to 5-FU resistance in gastric cancer." (PMID 36968583, 2023). "However, in gastric cancer, PTBP3 promotes metastasis of gastric cancer by regulating CAV1 and reduces the sensitivity of gastric cancer cells to 5-Fu by the HDAC6/Akt/TYMS pathway." (PMID 32477006, 2020). "More interestingly, whereas MUC1 rs4072037, ZBTB20 rs9841504, and TYMS rs2790 were suggested to improve the risk of noncardia gastric cancer (mainly the diffuse type) by 5- to 8-fold (P < 0.05*)." (PMID 27127881, 2016). "Thus, scholars suggest TYMS may be a potential biomarker for gastric cancer and response rates for the antifolate cytotoxic chemotherapy (i.e. raltitrexed, fluoropyrimidine) may be higher in patients with low expression of TYMS." (PMID 28056823, 2017). "The expressions of TYMS, TUBB3 and STMN1 were significantly associated with the clinicopathological characteristics of age, gender and family history of gastric cancer, but not with differentiation, growth patterns, metastasis and TNM staging in patients with gastric cancer." (PMID 28056823, 2017). "The GEPIA database was then utilized to further assess these TFs, highlighting HNF4A and RARA as highly expressed in stomach cancer (STAD), with subsequent analyses indicating a significant positive correlation between HNF4A and TYMS." (PMID 41326348, 2025). "Of these 12 genes, 7 genes highly expressed in gastric cancer tissues were down-regulated (ITGB5, TYMS, MYB, APOC1, CBX5, PLA2G2A, KIF20A) and 5 low-expressed genes were up-regulated after vorinostat treatment (SCGB2A1, TCN1, CFD, APLP1, NQO1." (PMID 21931799, 2011). "Expression of ITGB5, TYMS, MYB, APOC1, CBX5, PLA2G2A, and KIF20A which is up-regulated in human gastric cancer tissues, was significantly decreased by vorinostat." (PMID 21931799, 2011). "First, expression levels of TYMS regulating DNA synthesis and repair showed negative relation to drug sensitivity in gastric cancer and is a marker for drug resistance." (PMID 21931799, 2011).
gastric cancer (continued). "Moreover, gene expression analysis of gastric cancer identified a collection of genes (ITGB5, TYMS, MYB, APOC1, CBX5, PLA2G2A, and KIF20A) whose expression was elevated in gastric tumor tissue and downregulated more than 2-fold by vorinostat treatment in gastric cancer cell lines." (PMID 21931799, 2011). "Therefore, the present study was to investigate whether the genes ERCC1, BRCA1, TYMS, RRM1, TUBB3, STMN1 and TOP2A are underlying biomarkers for patients with gastric cancer, which, to our knowledge, has not been performed." (PMID 28056823, 2017).
lung cancer (34 papers, 2013 to 2025). A malignant neoplasm involving the lung. "There are >100 publications in PubMed that report resistance to pemetrexed in lung cancers associated with elevated TYMS levels or sustained benefit from pemetrexed in lung cancers associated with reduced TYMS levels." (PMID 37106126, 2023). "In all stratifications of the models, TYMS rs3819102, the most significant SNP associated with lung cancer (p = 0.007), was used." (PMID 35499292, 2022). "The TYMS 6 bp ins allele within the 3’UTR has been reported to contribute to a higher risk of lung cancer and we also observed a similar trend." (PMID 30939165, 2019). "The TYMS 3’UTR del/del genotype was associated with a lower lung cancer risk as compared to the ins/ins genotype (OR = 0.33, 95% CI: 0.11–0.96, P = 0.041)." (PMID 30939165, 2019). "Lung cancer patients with high expression levels of TYMS mRNA were associated with resistance to fluorouracil-based chemotherapy." (PMID 24649266, 2013). "An additional SNP in TYMS was found to interact with betaine to influence lung cancer risk in former smokers." (PMID 23372658, 2013). "TYMS rs3819102 conferred an increased risk of lung cancer in the additive model." (PMID 35499292, 2022). "In our study population, TYMS rs3819102 increased lung cancer risk in our study population and also showed importance in our lung cancer risk prediction models, especially among the population of males, people aged 60 and older, smokers, and people without a family history of cancer." (PMID 35499292, 2022). "TYMS played an essential role during the DNA synthesis, the alteration of TYMS might increase the risk of lung cancer, and the expression of TYMS confirmed the correlation with EGFR mutation in LUAD patients." (PMID 32684932, 2020). "Third, the rs3819102 polymorphism in TYMS might increase susceptibility to the risk of lung cancer." (PMID 32340630, 2020). "Gene expression analysis of the target genes using the GEPIA online tool revealed significant overexpression of DHFR and TYMS in lung cancer tissues in comparison to the normal controls (p < 0.05)." (PMID 38049779, 2023). "TYMS has been proposed recently to modulate the epithelial–mesenchymal transition in breast and lung cancer." (PMID 35740289, 2022). "After FDR adjustment, TYMS rs3819102 and BAG6 rs1077393 were significantly associated with lung cancer risk (p < 0.05)." (PMID 35499292, 2022). "The knockdown of TMPRSS4 in lung cancer cells induced the downregulation of thymidylate synthetase (TS)." (PMID 34379296, 2022). "The same with the results we have developed from bioinformatics, ALDOA, ENTPD2, LDHA, TYMS were significantly increased in 5 lung cancer cell line, comparing with in 16HBE." (PMID 33858449, 2021). "TYMS, a nucleotide synthetase, is commonly used as an indicator of chemotherapy sensitivity, that is its high expression in lung cancer often indicates insensitive for pemetrexed." (PMID 33129284, 2020). "TYMS, a key rate-limiting enzyme in the folate metabolism, plays essential roles in the development of several malignancies such as prostate cancer and lung cancer." (PMID 29100421, 2017). "TYMS has been extensively studied in lung cancer as a prognostic marker of survival and a predictive marker of response to pemetrexed and 5-FU." (PMID 26444668, 2015). "Folate genes implicated in lung cancer risk include methylenetetrahydrofolate reductase (MTHFR); thymidylate synthase (TYMS); serine hydroxymethyltransferase 1 (SHMT1); and cystathionine β-synthase (CBS)." (PMID 23372658, 2013). "A recent in vitro study mentioned that down-regulation of thymidylate synthase(TYMS) gene was found in pemetrexed-sensitive lung cancer cell lines." (PMID 24040222, 2013). "Further intersecting these predicted targets with transcriptomic datasets from breast, colorectal, and lung cancers highlighted hub proteins such as TYMS, AURKA, CDK1, and TK-1, which are critical regulators of DNA synthesis, mitotic progression, and cell cycle checkpoints." (PMID 40430485, 2025).
lung cancer (continued). "Furthermore, we found that pyrimidine metabolic rate–limiting enzymes CAD, RRM2, DTYMK, TYMS, TK2, and NR5C2 were all associated with the clinical outcomes of lung cancer and liver cancer." (PMID 32638267, 2020). "Similarly, the Kaplan-Meier survival analysis showed that pyrimidine metabolic rate–limiting enzymes DTYMK, NT5C3, RRM1, RRM2, TK1, TYMS, and UCK2 were all associated with adverse prognosis in the lung cancer." (PMID 32638267, 2020). "Our study may provide a theoretical evidence for individualized chemotherapy in advanced NSCLC and supports the use of detecting lung cancer tissue for TYMS expression to help us chose chemotherapy regimens." (PMID 24040222, 2013). "The protein expression levels of ALDOA, ENTPD2, LDHA, TYMS and CAT were investigated in 5 lung cancer cell lines (A549, H460, H1299, H1975, PC9), normal airway epithelial cells (16HBE) as control." (PMID 33858449, 2021). "And the pyrimidine metabolic rate–limiting enzymes DTYMK, NT5C3, RRM1, RRM2, TK1, TYMS, and UCK2 had particular values in lung cancer prognosis." (PMID 32638267, 2020). "In order to investigate how GYP exerts its anti-LC effects by regulating metabolites and metabolic pathways as well as enhancing the anti-lung cancer effects of chemotherapeutic agents, the relative contents of STAT3, EGFR, MAPK14, and TYMS between the six groups were analyzed by western blot." (PMID 36532716, 2022). "Recent studies revealed the role of TYMS in maintaining EMT in breast and lung cancer cells." (PMID 35740289, 2022).
non-small cell lung carcinoma (29 papers, 2011 to 2025). A group of at least three distinct histological types of lung cancer, including non-small cell squamous cell carcinoma, adenocarcinoma, and large cell carcinoma. "In another case, it was demonstrated that hsa-miR-1248 bound to the 3′-untranslated region of the TYMS rs2790G allele and inhibited its expression in non-small cell lung cancer in vitro, indirectly demonstrating a close relationship between hsa-miR-1248 and migration of tumors." (PMID 36248377, 2022). "Previous studies have shown that overexpression of TYMS in human non-small cell lung cancer (NSCLC) tumor cell lines reduced sensitivity to pemetrexed while downregulation of TYMS restored sensitivity of these cells to the proapoptotic effect of the drug." (PMID 37106126, 2023). "They found that the expression levels of Vimentin and ZEB1 were significantly decreased in TYMS knockdown human non-small cell lung cancer cell line A549 compared with the control cells." (PMID 35093082, 2022). "The studies about relationship between TYMS expression and effect of pemetrexed-based chemotherapy were comparatively few, and reports about prognostic significance of TYMS expression in advanced NSCLC non-small cell lung cancer are controversial." (PMID 24040222, 2013).